SLIRP (SRA stem-loop interacting RNA binding protein)
Description:
RNA-binding protein that acts as a nuclear receptor corepressor. Probably acts by binding the SRA RNA, and repressing the SRA-mediated nuclear receptor coactivation. Binds the STR7 loop of SRA RNA. Also able to repress glucocorticoid (GR), androgen (AR), thyroid (TR) and VDR-mediated transactivation.
Synonyms: C14orf156; DC50; PD04872
Tractability: Small molecule: a structure with a bound ligand is known. PROTAC: ubiquitination databases record sites on it; its protein half-life has been measured.
Gene: Protein-coding gene on chromosome 14 (77,708,045 to 77,761,104, forward strand). Ensembl gene ENSG00000119705.
Subcellular location: Mitochondrion; Nucleus
Subcellular location (Human Protein Atlas): Mitochondria
Pathways (Reactome):
Metabolism of RNA: Mitochondrial RNA degradation; Mitochondrial mRNA modification
Gene Ontology:
Molecular function: mRNA binding; protein binding; RNA binding; nucleic acid binding
Biological process: mitochondrial mRNA polyadenylation; negative regulation of mitochondrial mRNA catabolic process
Cellular component: mitochondrial matrix; mitochondrion; acrosomal vesicle; cytoplasm; nucleus; perinuclear region of cytoplasm; ribonucleoprotein complex; sperm flagellum
Genetic constraint (gnomAD): Loss-of-function variants: 12 observed, 13.63 expected, observed/expected ratio (o/e) 0.88, 90% interval 0.56 to 1.42. The upper end of that interval is the gene's LOEUF score, 1.42, which puts it in group 5 of 6, group 1 being the genes least tolerant of losing a copy. Missense variants: 142 observed, 130.41 expected, observed/expected ratio (o/e) 1.09, 90% interval 0.95 to 1.25. Synonymous variants: 53 observed, 47.4 expected, observed/expected ratio (o/e) 1.12, 90% interval 0.9 to 1.41.
Homologues: Orthologues: chimpanzee SLIRP (83% identical), macaque SLIRP (82% identical), dog SLIRP (70% identical), pig SLIRP (68% identical), mouse Slirp (67% identical), rat LOC108352643 (53% identical), tropical clawed frog slirp (46% identical), zebrafish slirp (42% identical).
Diseases named in the same sentence as SLIRP in open-access papers:
SLIRP is named in the same sentence as 16 diseases in open-access papers, as found by Europe PMC text mining. Sharing a sentence is not in itself a finding about the gene and the disease. The quoted sentences say what the papers report.
asthenospermia (2 papers, 2013 to 2020). "In sum, our data implicates SLIRP in regulating male fertility, wherein its loss results in asthenozoospermia associated with compromised sperm structure and mitochondrial morphology." (PMID 23976951, 2013). "The sperm DNA fragmentation rate was apparently increased in the asthenozoospermia group, which was negatively related to the SLIRP gene." (PMID 33150185, 2020). "The mRNA level and protein expression of SLIRP in the asthenospermia group were significantly reduced compared with those in the normospermia group." (PMID 33150185, 2020). "The expression of SLIRP is declined, oxidative damage is increased, and energy metabolism is decreased in spermatozoa of asthenospermia patients compared to normospermia participants." (PMID 33150185, 2020). "Compared to the normospermia group, SLIRP mRNA level and protein expression in sperm in the asthenospermia group were obviously decreased; also, the sperm progressive motility significantly declined." (PMID 33150185, 2020). "The expression of the SLIRP gene and protein in asthenospermia patients is downregulated." (PMID 33150185, 2020).
breast carcinoma (2 papers, 2016 to 2020). "SLIRP is also present in breast cancer, prostate cancer, and lung cancer tissues, and its expression is significantly enhanced in cancer tissues." (PMID 33150185, 2020).
prostate carcinoma (2 papers, 2019 to 2020). A carcinoma that arises from epithelial cells of the prostate gland. "The difference is statistically significant (p = 0.003 by Chi-square), and this result is consistent with the hypothesis that SLIRP loss promotes prostate cancer progression." (PMID 31819114, 2019). "The role of SLIRP in prostate cancer progression was investigated by exploratory analysis of clinical specimens." (PMID 31819114, 2019). "In androgen-sensitive LNCaP prostate cancer cells, immunoprecipitation of endogenous AR after DHT treatment or Ack1 expression demonstrated that association between AR and SLIRP is inhibited by DHT or Ack1 activation." (PMID 31819114, 2019). "The role of SLIRP in clinical progression of prostate cancer is uncertain and will require more investigation." (PMID 31819114, 2019). "The precise role of SLIRP in prostate cancer remains to be elucidated." (PMID 31819114, 2019).
colorectal cancer (1 paper, 2022). A primary or metastatic malignant neoplasm that affects the colon or rectum. "The co-expression analysis revealed that SLIRP is the top and highly co-expressed gene of PSMC1 which was shown to have prognostic roles in colorectal cancer." (PMID 35938038, 2022).
hypothyroidism (1 paper, 2023). Abnormally low levels of thyroid hormone. "In our study, SLIRP was up-regulated in hypothyroidism and only in nonsurvivors, possibly demonstrating the attempt to stabilize the mitochondria by maintaining adequate protein synthesis levels." (PMID 37249456, 2023). "Furthermore, some mitGenes with a concordant expression gain related to ATP production mechanism were shared between hypothyroidism and sepsis: SLIRP and TIMM8B appeared in sepsis nonsurvivor scenarios; ROMO1 and BLOC1S1 were present in both survivor and nonsurvivor scenarios." (PMID 37249456, 2023).
Leigh syndrome (1 paper, 2024). A progressive neurological disease defined by specific neuropathological features associating brainstem and basal ganglia lesions. "LRPPRC, a known gene that causes Leigh syndrome, is a mitochondrial protein that binds with its protein partner SLIRP and keeps the transcriptome of the mitochondria steady." (PMID 38448908, 2024).
metastatic tumors (1 paper, 2019). "Analysis of currently available data in cBioPortal showed that 6.9% of primary tumors (84 out of 1121) demonstrated SLIRP gene copy number loss while 11.4% of metastatic tumors (105 out of 918) demonstrated SLIRP gene copy number loss." (PMID 31819114, 2019).
mitochondrial encephalomyopathy (1 paper, 2023). A heterogenous group of disorders characterized by alterations of mitochondrial metabolism that result in muscle and nervous system dysfunction. "Clinical studies have demonstrated that mutations in the SLIRP gene cause mitochondrial encephalomyopathy, thus highlighting the crucial role of the SLIRP protein in maintaining proper mitochondrial function." (PMID 38203264, 2023).
Sepsis (1 paper, 2023). Sepsis is defined as life-threatening organ dysfunction caused by a dysregulated host response to infection. "Finally, we demonstrated that ROMO1, SLIRP and TIMM8B could be predictive biomarkers in children's sepsis." (PMID 37249456, 2023). "BLOC1S1, ROMO1, SLIRP and TIMM8B mitGenes showed the capability to distinguish sepsis survivors and nonsurvivors." (PMID 37249456, 2023). "In adult sepsis, BLOC1S1, ROMO1, SLIRP and TIMM8B showed excellent ability to identify nonsurvivor samples." (PMID 37249456, 2023).
mitochondrial disease (1 paper, 2024). "Although pathogenic mutations in the LRPPRC and SLIRP genes cause devastating human mitochondrial diseases, the in vivo function of the corresponding proteins is incompletely understood." (PMID 39087558, 2024).
SLIRP also shares sentences with these, for which no sentence is quoted: cancer (2 papers); breast adenocarcinoma (1); infection (1); lung adenocarcinoma (1); lung carcinoma (1); tumor (1).